MCL1 (MCL1 apoptosis regulator, BCL2 family member)
Diseases named in the same sentence as MCL1 in open-access papers (continued):
Sharing a sentence is not in itself a finding about the gene and the disease.
acute lymphoblastic leukemia (26 papers, 2011 to 2025). Leukemia with an acute onset, characterized by the presence of lymphoblasts in the bone marrow and the peripheral blood. "AZD4320, a dual BCL-2 and BCL-XL inhibitor, and AZD5991, which targets MCL-1, induce cell death in acute lymphoblastic leukemia cells when combined." (PMID 40662801, 2025). "Increased MCL1 and USP9X protein expression has been detected during relapses of AML, acute lymphocytic leukemia (ALL) and MM, and is associated with increased tumor survival." (PMID 32354135, 2020). "For instance, T cell acute lymphoblastic leukaemia cell lines displayed resistance to doxorubicin, which was demonstrated to be dependent on Mcl-1 pro-survival protein expression through α2β1 integrin signalling." (PMID 29304770, 2018). "We tested the apoptotic sensitivity of BCR-ABL-expressing B-lineage acute lymphoblastic leukemia cell lines engineered to depend on Bcl-2, Bcl-xL, Mcl-1 or Bfl-1 overexpression for survival." (PMID 28594323, 2017). "In fact, in B Cell acute lymphoblastic leukemias (B-ALL), where Mcl-1 overexpression is a defining characteristic, FAO is a critical fuel source." (PMID 37521407, 2023). "Deletion of FBXW7 or its functional inactivation in acute lymphoblastic leukemia (ALL) cells, impairs MCL1 degradation in response to DNA-damaging agents, resulting in MCL1 overexpression and evasion of apoptosis." (PMID 35345853, 2022). "In T-cell acute lymphoblastic leukemia (T-ALL), the collagen-binding integrin α2β1 promotes doxorubicin resistance by maintaining the levels of anti-apoptotic protein, myeloid cell leukemia-1 (Mcl-1) through the inhibition of the c-Jun N-terminal Kinase (JNK) activation." (PMID 31857649, 2019). "We have previously demonstrated that the anti-apoptotic activity of endogenous Mcl-1 is essential to maintain the survival of murine BCR-ABL-expressing B-lineage acute lymphoblastic leukemia (B-ALL) cell lines despite the concomitant expression of other anti-apoptotic molecules." (PMID 26862853, 2016). "Indeed, in acute lymphoblastic leukemia (ALL), obatoclax provokes disruption of the interaction between MCL1 and BECN1, inactivation of MTOR, and activation of the necroptotic cell death." (PMID 34830777, 2021). "In particular, Fenretinide has been reported to eliminate ABT-737-resistant cell lines via ROS generation and MCL1 reduction and thus has synergetic effect with ABT-737 to enhance mitochondrial apoptotic cascade in acute lymphoblastic leukemia (ALL)." (PMID 35851420, 2022). "Acute lymphoblastic leukemia (ALL) T cells exhibited an increased survival rate and an enhanced migration upon stimulating their α2β1 integrins with collagen type I in a mechanism dependent upon ERK1/2 MAPK activation and maintenance of the Bcl-2 family member, prosurvival protein, Mcl-1." (PMID 35681441, 2022). "Genetic and pharmacologic inhibition of STAT5 activity decreases expression of apoptosis inhibitors MCL1 and BCL2 and inhibits leukemogenesis of BCR-ABL1+ acute lymphoblastic leukemia (ALL), both in cell lines and newly diagnosed and relapsed/TKI-resistant ALL patients." (PMID 31684144, 2019). "In fact, a recent study using CMAP showed that LY294002, a PI3K inhibitor, and gossypol and AT-101, MCL1 or other anti-apoptotic BCL-2 family member inhibitors, were capable of reversing the prednisolone-resistance of MLL-rearranged Acute Lymphoblastic Leukemia (ALL) in infants." (PMID 27746730, 2016).
breast tumor (26 papers, 2006 to 2025). "Alongside the requirement of MCL-1 for breast tumor growth, MCL-1 has also been implicated in acquired resistance to tamoxifen or fulvestrant treatment in ER-positive breast cancer cell lines." (PMID 35349392, 2022). "Collectively, our results demonstrate that the combination of targeting the PI3K pathway through inhibition of PI3Kβ or AKT and activating the pro-apoptotic pathway through inhibition of Mcl-1 is able to deliver greater anti-tumour benefit in vivo at tolerable doses in PTEN-deficient breast tumors." (PMID 36241868, 2022). "Studies have confirmed the functional role of Mcl-1 in breast tumor development and revealed Mcl-1 expression is a necessity in breast tumorigenesis." (PMID 35053443, 2022). "For example, the Mcl-1 protein is frequently overexpressed in breast tumors, and it has been found to correlate with a bad prognosis." (PMID 33503929, 2021). "Increased expression and activity of Mcl-1 was similarly seen in clinical breast tumor specimens treated with AI + the selective estrogen receptor downregulator fulvestrant." (PMID 29343814, 2018). "We investigated the importance of MCL-1 copy number variations and expression in breast tumors using publically available datasets." (PMID 27931239, 2016). "KLF4/5 were positively correlated with MCL1 in primary breast tumors, and enforced expression of MCL1 was sufficient to rescue the lapatinib sensitivity of KLF4/5-deficient cells." (PMID 25789974, 2015). "In order to determine the correlation of Myc with MCL1, IHC staining of Myc and MCL1 was performed in 142 breast tumor tissue array samples and the staining was graded as weak positive (G I), medium positive (G II) and strong positive (G III)." (PMID 24564888, 2014). "Previous studies have shown that the Mcl-1 gene is located on chromosome 1q21 and is frequently amplified in many cancers including breast tumors." (PMID 24971890, 2014). "Mcl-1 is an anti-apoptotic Bcl-2 family member that is often over expressed in breast tumors, correlating with poor survival." (PMID 24971890, 2014). "Sorafenib downregulates Mcl-1 protein levels in a time- and dose-dependent manner to induce apoptosis in renal, colon and breast tumour lines." (PMID 16880785, 2006). "Expression of mutant forms of BH3-mimicking proteins could bind to Mcl-1 and inhibit the metastasis and invasion of TN breast tumor cell lines in xenograft models." (PMID 37736508, 2023). "Silencing MCL1 in breast tumor xenografts reduced tumor growth." (PMID 35053443, 2022). "In addition to the bifurcation of GFRN and drug response, breast tumor cells of the growth phenotype showed a higher response to the specific MCL-1 inhibitor UMI-77." (PMID 28446242, 2017). "Specifically, breast tumors classified as the growth phenotype may overexpress MCL-1 and inhibit BIM expression to achieve cell survival." (PMID 28446242, 2017). "Taken together, our study provided wider insight into the deeper role of WNT5B-triggered WNT/β-catenin signaling; it might regulate breast tumor progression and outcome by modulating mitochondrial physiology through MCL1." (PMID 24564888, 2014). "For example, aberrant STAT3 signaling promotes breast tumor progression through deregulation of the expression of downstream target genes, which control proliferation (Bcl-2, Bcl-xL, survivin, cyclin D1, c-Myc, and Mcl-1), angiogenesis (Hif1α and VEGF), and EMT (vimentin, Twist, MMP-9, and MMP-7)." (PMID 36446524, 2023). "Signaling through MEK/ERK has been shown to induce transcription of MCL1 via ELK-1 and SRF transcription factors, and this pathway is commonly dysregulated during breast tumor development." (PMID 35349392, 2022). "Across 890 breast tumors, the transcript abundance for KLF4, KLF5 and MCL1 was positively correlated." (PMID 25789974, 2015).
breast tumor (continued). "This study demonstrates that different resistance drivers to PI3Kβi and AKTi converge to reactivate PI3K-AKT or mTOR signalling and combined inhibition of Mcl-1 and PI3K-AKT has potential as a treatment strategy for PI3Kβi/AKTi sensitive and resistant breast tumours." (PMID 36241868, 2022). "More recently, MCL-1 was shown to be widely expressed in breast tumours, regardless of subtype or ER status although these studies did not report patient outcome." (PMID 29339815, 2018). "Not surprisingly, breast tumors frequently dysregulate this pathway to favor tumor cell survival, often through upregulation of anti-apoptotic Bcl-2 family proteins (Bcl2-A1, Bcl-2, Bcl-xL, Bcl-w, and Mcl-1)." (PMID 31595181, 2019). "Thus, MCL-1 inhibitors are beneficial for targeted apoptosis of breast tumor ecosystems, even in a subtype where MCL-1 dependency is not intrinsically driven by oncogenic pathways." (PMID 30631150, 2019). "In contrast to the observation in human breast tumor cells, we could not detect MCL-1 degradation upon paclitaxel treatment in MEFs and mouse mammary epithelial cells." (PMID 23577147, 2013).
bladder cancer (24 papers, 2012 to 2025). "Similarly, OSU-T315, an inhibitor of integrin-linked kinase, was observed to inhibit Mcl-1 expression levels via targeting the GSK-3β/FBXW7 axis in bladder cancer cells." (PMID 37215134, 2023). "Stevioside was identified by high-throughput screening as a useful compound to increase cell apoptosis via activation of GSK-3β and induction of FBXW7, contributing to downregulation of MCL-1 in bladder cancer." (PMID 37215134, 2023). "In this report, we have identified the FL118 differential modulation of apoptosis and the expression of anti-apoptotic proteins (survivin, XIAP, Mcl-1) in FL118-sensitive versus FL118-insensitive bladder cancer cells." (PMID 33217967, 2020). "Obatoclax antagonizes Mcl-1 and induces cell death in hematological tumors, so we decided to study obatoclax effects in paclitaxel-sensitive and paclitaxel-resistant bladder cancer cells." (PMID 30563080, 2018). "Downregulation of antiapoptotic proteins Bcl-2 and Mcl-1 by Hd-Sb in bladder cancer cells was also observed." (PMID 26989427, 2016). "Taken together, BIX-01294 decreases the expression of USP9X and promotes the degradation of MCL1, which eventually leads to apoptosis in bladder cancer cells." (PMID 25685062, 2015). "In summary, our data demonstrate that BIX-01294 induces ER stress pathway, resulting in up-regulation of PMAIP1 and down-regulation of USP9X and MCL1, leading to apoptosis in bladder cancer cells." (PMID 25685062, 2015). "According to our present study, we demonstrate that BIX-01294 causes apoptosis in bladder cancer cells through ER stress pathway, resulting in PMAIP1 up-regulation and MCL1 down-regulation." (PMID 25685062, 2015). "Anti-apoptotic members such as Bcl-2, Bcl-xL, Bcl-w and Mcl-1 are highly overexpressed in many malignancies including bladder cancer are known to adversely affect chemosensitivity and radiosensitivity." (PMID 25885284, 2015). "To determine the importance of MCL1 in the process of apoptosis induced by BIX-01294, we overexpressed MCL1 gene in human bladder cancer cells and then treated with BIX-01294 for 24 hours." (PMID 25685062, 2015). "More importantly, knockdown of S6K1 effectively reduced the levels of Mcl-1 in bladder cancer cells, suggesting that Mcl-1 is a downstream target of S6K1." (PMID 24566141, 2014). "Time course analysis demonstrated that Mcl-1 reduction occurred at about 4 h and was sustained up to 24 h in both bladder cancer cells after evodiamine treatment." (PMID 24566141, 2014). "In the present study, we observed that evodiamine blocked TRAIL-induced Mcl-1 upregulation in bladder cancer cells." (PMID 24566141, 2014). "Mcl-1 may have major roles in the distinct responses to paclitaxel in these bladder cancer cells and, therefore, is a good candidate to predict paclitaxel response in the clinical setting." (PMID 30563080, 2018). "As mentioned, Mcl-1 may mediate paclitaxel resistance in bladder cancer cells and is highly expressed in many muscle-invasive bladder carcinomas." (PMID 30563080, 2018). "Moreover, qRT-PCR results revealed that three STAT3 direct target genes (bcl2, bclxl and mcl1) were downregulated at mRNA levels in both two bladder cancer cell lines, indicating that the reduction is mainly due to the transcriptional regulation." (PMID 25849286, 2015). "Remarkably, BIX-01294 can enhance the amount of PMAIP1 and reduce MCL1 in bladder cancer cells." (PMID 25685062, 2015). "In sum, these findings indicate that WDR5 enhances bladder cancer cell anti-apoptosis and chemoresistance to cisplatin by regulating MCL1 and BIRC3, and it may be a potential target for drug development." (PMID 25656485, 2015). "To elucidate the underlying mechanism, we found that evodiamine significantly reduced the protein levels of Mcl-1 in 253J and T24 bladder cancer cells, and overexpression of this molecule attenuated the apoptosis induced by evodiamine alone, or in combination with TRAIL." (PMID 24566141, 2014).
bladder cancer (continued). "Furthermore, Mcl-1 is overexpressed in many invasive bladder carcinomas, and it is related to tumor progression, so Mcl-1 expression may be of predictive value in bladder cancer." (PMID 30563080, 2018). "Moreover, Mcl-1 expression was analyzed by immunohistochemistry in bladder carcinoma tissues." (PMID 30563080, 2018). "Moreover, overexpression of Mcl-1 attenuated the ability of evodiamine to induce apoptosis, supporting the notion that the downregulation of Mcl-1 played an important role in evodiamine-induced apoptosis in bladder cancer cells." (PMID 24566141, 2014). "Finally, Mcl-1 expression may be a useful predictive biomarker in advanced bladder cancer." (PMID 30563080, 2018). "Exosome-derived microRNA29c induces apoptosis in bladder cancer cells by down-regulating BCL-2 and MCL-1." (PMID 27517627, 2016). "Mechanistically, WDR5 regulated various functions in bladder cancer by mediating the transcription of cyclin B1, cyclin E1, cyclin E2, UHMK1, MCL1, BIRC3 and Nanog by histone H3 lysine 4 trimethylation." (PMID 25656485, 2015). "Thus, inhibition of mTOR/S6K1 activity may be an effective strategy for sensitizing cancer cells to apoptotic stimuli, and mTOR/S6K1-mediated downregulation of Mcl-1 is supposed to be responsible for the evodiamine-mediated enhancement of TRAIL-induced apoptosis in bladder cancer cells." (PMID 24566141, 2014). "In conclusion, we herein demonstrate for the first time that evodiamine induces apoptosis and enhances TRAIL-induced apoptosis in human bladder cancer cells, possibly through mTOR/S6K1-mediated downregulation of Mcl-1." (PMID 24566141, 2014). "We found that bladder cancer cells with a mutant Kras is highly sensitive to FL118-induced cell growth inhibition and cell death induction through inhibiting the anti-cancer cell death and drug resistance factors (survivin, Mcl-1, XIAP)." (PMID 33217967, 2020). "Accordingly, we used immunohistochemistry to analyze the expression of Mcl-1 in biopsies from 72 bladder carcinomas (53 non-muscle-invasive, 19 muscle-invasive)." (PMID 30563080, 2018). "In the present study, overexpression of Mcl-1 attenuated the synergistic induction of apoptosis by the combination of evodiamine and TRAIL, suggesting that downregulation of Mcl-1 may be responsible for evodiamine-mediated enhancement of TRAIL-induced apoptosis in bladder cancer cells." (PMID 24566141, 2014).
renal carcinoma (20 papers, 2010 to 2025). A carcinoma arising from the epithelium of the renal parenchyma or the renal pelvis. "Taken together, these results provide the first evidence that lucanthone enhances TRAIL-induced apoptosis through DR5 upregulation by downregulation of miR-216a-5p and DUB3-dependent Mcl-1 downregulation in human renal carcinoma cells." (PMID 35008442, 2021). "PVT1 knockdown promoted apoptosis, inhibited renal cancer cell proliferation, decreased Mcl-1, and increased cleaved caspase-3 and cleaved PARP." (PMID 29254209, 2017). "Rather than enhancing transcriptional activity of the Mcl-1 promoter, our data showed that PVT1 enhanced the stability of Mcl-1 mRNA in renal cancer cells." (PMID 29254209, 2017). "Western blot of cleaved PARP and cleaved Caspase-3 revealed that Mcl-1 promotes PVT1-induced renal cancer cell growth and inhibits apoptosis in vivo." (PMID 29254209, 2017). "Combined treatment with sorafenib and kahweol potentiated the cytotoxicity in renal carcinoma cells through down-regulation of Mcl-1 and c-FLIP protein expression in a proteasome-dependent manner." (PMID 29137334, 2017). "Taken together, these results suggest that eupafolin enhanced TRAIL-mediated apoptosis via down-regulation of Mcl-1 and up-regulation of Bim in renal carcinoma Caki cells." (PMID 27582546, 2016). "The multikinase inhibitor sorafenib, an approved drug for the treatment of renal cancer, has been shown to downregulate the expression of mcl-1 at both the transcriptional and posttranscriptional level." (PMID 20105315, 2010). "This may provide a good opportunity for further exploration of MCL-1 as a biomarker and target in kidney/renal cancer." (PMID 34384473, 2021). "We also showed that PVT1 inhibits renal cancer cell apoptosis by enhancing Mcl-1 mRNA stability." (PMID 29254209, 2017). "Interestingly, a recent study showed that inactivation of MCL-1 by a NOXA-dependent pathway sensitized renal cancer cells to chemotherapeutic agents." (PMID 27655686, 2016). "Cafestol, one of the major compounds in coffee beans, has been reported to have anti-carcinogenic activity and tumor cell growth-inhibitory activity, and we examined whether cafestol could overcome resistance against ABT-737 in Mcl-1-overexpressed human renal carcinoma Caki cells." (PMID 25375379, 2014). "By downregulating Mcl-1 and c-FLIP through ROS, berberine has been reported to promote TRAIL-induced apoptosis in human renal cancer cells." (PMID 36144625, 2022). "To investigate the role of apoptosis-related proteins in BMI-1026-induced apoptosis, we used human renal carcinoma Caki cells engineered to overexpress Bcl-2 (Caki/Bcl-2), c-FLIP (L) (Caki/c-FLIP (L)), and Mcl-1 (L) (Caki/Mcl-1 (L))." (PMID 33924053, 2021). "Therefore, Mcl-1 may represent a good target for TRAIL-based therapies in renal carcinomas." (PMID 33841136, 2021). "miR-29b overexpression in CD8+ T cells of renal carcinoma patients has been found to induce immune dysfunction through down-regulation of JAK3 and MCL-1." (PMID 29579063, 2018). "Taken together, our results suggested that YM155 sensitizes TRAIL-mediated apoptosis via down-regulation of Mcl-1 and c-FLIP expression in renal carcinoma Caki cells." (PMID 27528031, 2016). "PVT1 increased Mcl-1 mRNA levels in renal cancer cells by promoting mRNA stability without influencing its transcription." (PMID 29254209, 2017). "In conclusion, our results suggested that YM155 induces TRAIL-mediated apoptosis through cathepsin S-dependent down-regulation of Mcl-1 expression and down-regulation of c-FLIP expression via down-regulation of NF-κB transcriptional activity in human renal cancer cells." (PMID 27528031, 2016).